CD4 (CD4 molecule)
Diseases named in the same sentence as CD4 in open-access papers (continued):
Sharing a sentence is not in itself a finding about the gene and the disease.
lymphoma (continued). "In a mouse lymphoma model, a similar MIP3α-OFA vaccine showed the CD8+ T-cell effector response to be essential for protection with the CD4+ T-cell effector response being expendable." (PMID 28018602, 2016). "Lymphoma cells were positive for the T-cell marker CD3, but aberrantly expressed CD4 and CD8 compared with thymocytes from unirradiated mice." (PMID 26399548, 2015). "The greater degree of oligoclonal expansion observed in the infected CD8+ T cells, contrasts with the CD4+ phenotype of ATL; cases of CD8+ adult T-cell leukaemia/lymphoma are rare." (PMID 26552867, 2015). "The lymphoma cells displayed a CD3ε/CD56/TIA-1/granzyme-B/Perforin-positive and CD20/CD79a/CD4/CD8-negative immunophenotype and positive for Epstein-Barr virus by EBER in situ hybridization." (PMID 24886075, 2014). "Tumor cells expressed surface CD4 and CD8 with variable amounts of surface TCRβ, implying that these lymphomas originated from immature thymocytes." (PMID 24753404, 2014). "The soluble form of CD4 (sCD4) can block HIV-1 and HIV-2 infection in human lymphoma cell lines, but it enhances SIVagm infection in these cell lines by 10 to 100-fold." (PMID 24278125, 2013). "Pathological analysis showed that this tumor was a lymphoma with atypical morphology, and by immunohistochemical methods, it was found that these cells were CD3+ CD4+." (PMID 24156738, 2013). "However, systemic lymphomas may occur at virtually any level of CD4 cell count, BL occurring more frequently in patients with moderate/advanced immunodepression (200–500 CD4 cells/μl) and PCNSL occurring in patients with severe immunodepression (<200 CD4 cells/μl)." (PMID 24151490, 2013). "The CD4, CD8 and TCRβ phenotype of cells in the Fli-1 thymus, liver and lymph node suggested that the disease was a T cell lymphoblastic leukaemia/lymphoma (pre-T LBL)." (PMID 23667468, 2013). "At the time of lymphoma diagnosis the HIV-RNA values were <50 RNA-copies per mL blood (undetectable) and the CD4-positive cell count 170 ×106/L." (PMID 23880011, 2013). "Infection of CD4+ T cells by HTLV-1 is therefore thought to play a pivotal role in HTLV-1-related pathogenicity, including leukemia/lymphoma of CD4+ T cells and chronic inflammatory diseases." (PMID 22647666, 2012). "Our flow cytometric data shows decreases in CD4 and CD8 cell population in the advanced stages of lymphoma development." (PMID 22312355, 2011). "These CD4+ tumors express high levels of CD30, a tumor necrosis factor receptor II family member, also over-expressed on human lymphomas with diverse etiologies." (PMID 21573129, 2011). "All of the lymphomas in HBZ-Tg mice were CD3+ and CD4+ by immunohistochemical analyses when examined before the mice became moribund." (PMID 21347344, 2011). "In recent years an increase of functional CD4+CD25+ regulatory T cells (Treg cells) has been established for patients withsolid tumors, acute leukemias, and lymphomas." (PMID 21904560, 2011). "There is a significant relationship between the subtype of lymphoma and the HIV disease status, with diffuse large B-cell lymphoma occurring in the setting of profound immunodepression (CD4<100.106/L) and Burkitt lymphoma in less immunodeficient patients." (PMID 20066157, 2010). "RUNX3 is required for silencing of CD4, and our results suggest that this silencing plays a significant role in RUNX3-induced progression of lymphomas." (PMID 18358079, 2008).
lymphoma (continued). "Although PCNS lymphoma can develop in HIV-negative individuals, it much more often occurs in severely immunosuppressed HIV-infected persons (CD4+ T cell counts <50/μl)." (PMID 17388662, 2007). "A substantial heterogeneity wasseen in the intensity of CD4 and CD8 expression among various lymphomas, which wasindependent of the level of CD3 expression." (PMID 1322753, 1992). "The retention of these markers (despite switching from CD8+ to CD4+) supports our belief that the large cells are indeed a product of a phenotypical shift from the prior lymphoma rather than a de novo presentation." (PMID 40166794, 2025). "Co-culturing EBV+ JiJoye lymphoma cells with CD4+ T cells or with peripheral blood mononuclear cells (PBMCs) downregulates CD4+ T cell functions, but the depletion of IRF4 in EBV+ JiJoye lymphoma cells reduces PD1 and PD-L1 expression, and partially restores CD4+ T cell functions." (PMID 40733503, 2025). "These TCRs, when engineered into CD8+ and CD4+ T-cells, restored cytotoxic activity against EBV-infected cells and may serve as a foundation for adoptive T-cell therapies in EBV-driven lymphomas, including cHL." (PMID 40361360, 2025). "In our case, the finding of a polyclonal lymphocytic population in the CSF and an increased CD4/CD8 T cell ratio in the blood ruled out the diagnosis of lymphoma and strengthened the suspicion of granulomatosis." (PMID 40115709, 2025). "Furthermore, all our patients presented with advanced lymphomas (stage III/IV) and severe HIV immunosuppression (CD4 counts < 200/mm3)." (PMID 40606992, 2025). "Within lymphomas, the single responder exhibited higher CD4+ T-helper cell counts and a high CD4/CD8 ratio, while non-responders showed elevated activated T-cell counts." (PMID 41050077, 2025). "In this mouse model without immunosuppression, there was not a significant incidence of lymphomas, but with CD4 depletion, there was." (PMID 39339897, 2024). "Combinatory treatment with CpG-Stat3 siRNA and CTLA4 antibody in A20 lymphoma tumor-bearing mice significantly increased the percentages of IFNγ and/or granzyme B (GZMB) producing CD4+ T cells and CD8+ T cells in tumors compared to either CpG-Stat3 siRNA or CTLA4 antibody alone." (PMID 39618825, 2024). "In this study 12/155 (7.7%) of the mice developed lymphoma with CD4 depletion, while none of the mice in the other treatment groups developed lymphoma." (PMID 39339897, 2024). "The third negative patient had lymphoma treated with rituximab (216 CD4 T cells and 196 CD8 T cells per mm3 but no B cells)." (PMID 39086476, 2024). "The CD20+CXCR4hiCD24+CXCR5+CD40+CD4+ B-cell population in MC23 of HIV+ pre-NHL (cART-naïve) samples displayed a mature and activated phenotype (IgM+HLADR+) with a potential pre-lymphoma feature as it expressed AICDA compared to MC23 of HIV+ cART-naïve samples." (PMID 39324141, 2024). "The lymphoma develops in the spleen and lymph nodes and no traces or very few malignant CD4 T cells and CD8 T cells can be detected in the blood circulation." (PMID 39272178, 2024). "Interestingly, our patient's initial CD4 count was 1, which improved to 96 after five months of HAART, raising concerns for IRIS lymphoma." (PMID 38854279, 2024). "The link between EBV infection and lymphoma development in HIV patients could be utilized advantageously with accurate disease identification and prognosis being determined using CD4 counts in conjunction with EBV viral loads." (PMID 38339297, 2024). "Notably, compared to lymphoma patients, a higher abundance of γδT cells in myeloma patients with t-SNE analysis was identified in the compartments of CD4, CD8 and Tfh cells." (PMID 37187728, 2023). "One HIV-positive SARS-CoV-2 naive donor with a low CD4 T cell count of 40 cells/μL on cART, and one individual with relapsed lymphoma, both had no detectable humoral and cellular responses after 2 or 3 doses of mRNA vaccine." (PMID 36590902, 2023).
lymphoma (continued). "Flow cytometric analysis of peripheral blood showed the majority of lymphocytes were CD3+ cells (95.4%) and a CD4/CD8 ratio of 27.4:1 (range, 0.5–2:1), with the majority of CD4+ cells (92.9%) showing a CD7–CD26– phenotype, indicating the peripheral blood involvement of lymphoma." (PMID 36649072, 2023). "The development of v-ABL induced B-cell leukemia/lymphoma was confirmed in all mice by the presence of characteristic B220+/CD19+/CD43+ leukemic progenitor B cells, except for one WT mouse which developed CD4+CD8- T cell leukemia." (PMID 35597806, 2022). "Next, we examined whether in vitro-expanded CD4+ T and CD8+ T cells stimulated with iCL exhibit cytotoxic activity against the lymphoma cells." (PMID 36077655, 2022). "When naïve CD4+ T cells and CD8+ T cells separately co-cultured with LMP1/2A+ B lymphoma cells for 24 days, both CD4+ T cells and CD8+ T cells exhibited cytotoxicity against those LMP1/2A+ lymphoma cells." (PMID 36077655, 2022). "It is well documented that a drop in CD4 T-cell count increases the risk of NHL dramatically, but unlike most other HIV-associated lymphomas, HIV-associated BL risk is higher for patients with a relatively high CD4 T-count." (PMID 34705104, 2022). "However, only a lower CD4/CD8 ratio could predict inferior OS (HR = 2.103, 95% CI = 1.156–3.827, P = 0.015) and PFS (HR = 1.853, 95% CI = 1.030–3.334, P = 0.040) independently in the multivariate analysis, adjusted for the lymphoma- and HIV-associated parameters." (PMID 35873145, 2022). "The univariate analysis identified that the lymphoma and HIV-related parameters, including LDH, ECOG PS, Ann Arbor stage, bulky mass, B symptoms, IPI, aaIPI, NCCN-IPI, CD4 T-cell count, erythrocyte sedimentation rate (ESR), and albumin (ALB), had a significant impact on OS (all P < 0.05)." (PMID 35873145, 2022). "Its role in T-cell leukemia/ lymphoma is largely unknown, but THEMIS was recently shown to be downregulated by promoter methylation in HTLV-1-infected CD4-positive cells of adult T-cell leukemia." (PMID 36376973, 2022). "nTFHL-NOS is the recommended term for CD4+ lymphomas with TFH phenotype but that do not meet criteria for nTFHL-AI or nTFHL-F." (PMID 35732829, 2022). "We performed RNAseq analysis of three groups: 1-in vitro wild type CD4+ activated lymphocytes [n = 3], 2-in vitro NPM-ALK-engineered CD4+ lymphocytes [n = 3] and 3-in vivo-derived CD4+ lymphoma cells purified by flow cytometry to isolate CD3+ [n = 3] and CD3- populations [n = 3]." (PMID 35246138, 2022). "For the three patients without CD4+ counts, the lymphoma IR (all in category C) was 0.20 per 1000 children-year (95% CI, 0.04–0.59)." (PMID 36551614, 2022). "CD4+ cases lack the phenotype of TFH cells (as in primary cutaneous CD4+ small/medium-sized pleomorphic T-cell lymphomas) and Treg cells (as in adult T-cell leukaemia/lymphoma), which lends no support to an origin from these cellular subsets." (PMID 35626087, 2022). "Recently, preclinical data reported the superiority of Tscm CAR-T cells (CD4+CD8+CD62L+CD45RA+) with respect to bulk T cells (CD4+CD8+) in terms of antitumor activity and expansion capacity in xenograft mouse models of leukemia and lymphoma." (PMID 36358770, 2022). "Low CD4+ lymphocyte counts and the absence of cART treatment prior to lymphoma are considered factors of worse prognosis." (PMID 34771697, 2021). "Nevertheless, CD4+ T-helper cells from αDEC205-BZLF1 expressed the T-helper 1 phenotype (Tbet+ and IFNγ+) which might be supportive of lymphoma prevention and favorable outcome." (PMID 34073261, 2021). "To improve upon this, we investigated the lymphoma microenvironment and found that the lack of intrafollicular CD4 + memory T cells plays a critical role in treatment failure." (PMID 34267181, 2021). "In CD4+ T-cells, the central memory (CM) phenotype fraction was generally larger compared to CD8+ T-cells, but we still observed a similar shift from naive T-cells to EM phenotype in B-cell depleted lymphoma patients." (PMID 34235400, 2021).
lymphoma (continued). "The fraction of CD4+ cells was increased in FYN-TRAF3IP2-driven lymphomas and there were no changes in the number of CD8+ cells." (PMID 34140493, 2021). "In the first model, AITL-like lymphoma did not naturally develop: bone marrow transplantation from Tet2-Rhoa-CD4 mice to syngenic mice followed by immunization with sheep red blood cells (SRBCs) was required for development of AITL-like lymphoma in recipients." (PMID 32704161, 2020). "Double positive CD4+CD8+ T-cells were the dominant population in eight out of 12 lymphomas, whereas non-lymphomatous lesions showed no dominant lymphoid population in five out of eight cases." (PMID 32903608, 2020). "In only one case (CD4+CD8+ double positive lymphoma) it scored positive for FeLV while FIV was negative in all three cases." (PMID 32903608, 2020). "Unlike dogs, the high prevalence of CD4+CD8+ lymphomas in cats it makes difficult to differentiate lymphoma from non-lymphomatous lesions using FC alone." (PMID 32903608, 2020). "Foxo1 and Foxo3 in CD4+ T cells are the most important among Foxo family members because the T-DKO mice are lethal from eight weeks of age due to immunological disturbance, leading to lymphoma, enteritis, and digestive malabsorption." (PMID 31756626, 2019). "CD4-NPM-ALKLCKΔΔTyk2 lymphomas failed to grow in vitro in contrast to tumor cells isolated from CD4-NPM-ALK mice." (PMID 30131584, 2019). "Notwithstanding, E.G7 lymphoma cells were shown for the first time to reduce dendritic cell activation of peptide-specific CD4+ T cells through a soluble factor rather than a cell contact-dependent mechanism." (PMID 31602007, 2019). "The DOX-loaded micelles were small (<120 nm), showed sustained drug release, and triggered significantly large numbers of total CD4+/CD8+ T cells and functional CD4+/CD8+ T cells in mice with lymphoma than the same micelles without DOX." (PMID 31379579, 2019). "Interestingly, in lymphomas from CD4-NPM-ALKLCKΔΔTyk2 mice, MCL1 expression was decreased at both the mRNA and protein levels as compared to CD4-NPM-ALK mice expressing TYK2 (P < 0.0001)." (PMID 30131584, 2019). "Moreover, deletions of CD4+ and CD8+ T cells positive for some TCR-Vβ families were also observed in HIV+ patients with lymphoma, in whom they can have a greater impact." (PMID 30337929, 2018). "Cultures exposed to the polyclonal stimulus (PMA + ionomycin) showed that CD4+ T cells from HIV+ patients with lymphoma were not able to produce TNF-α, IFN-γ, and/or IL-2 (p < 0.05)." (PMID 30337929, 2018). "LAG-3 expression could be substantially upregulated on CD4+ or CD8+ T cells by IL-12, a cytokine that has been shown to induce T-cell exhaustion and be increased in the serum of lymphoma patients." (PMID 28977875, 2017). "Furthermore, a marked difference in the histopathology and simultaneous CD4 and CD8 positivity excluded lymphoma." (PMID 26064745, 2015). "Of the 60 mice with lymphomas analyzed by flow cytometry, 57 mice had both CD4+CD8+ double positive and CD8+ single positive T cells, while two mice with lymphomas had predominantly CD8+ cells and one mouse had predominantly CD4+CD8+ double positive cells in the thymus, spleen, and lymph nodes." (PMID 23457589, 2013). "We identified an MHC class II-restricted CD4+ T-cell epitope and therein an MHC class I-restricted CD8+ T-cell epitope (SSPQGSPEPL) that, after prime/boost immunization, protected up to 25% of mice against a lethal lymphoma challenge." (PMID 24130880, 2013). "The initial finding was that of a blastic EBV-positive lymphoma primarily detected in effusions, lacking obvious B- and T-cell markers except CD4 but showing evidence of plasma cell differentiation as indicated by positivity for CD38 and CD138." (PMID 23880011, 2013). "However, minimal variations in the recovery rate of CD4+ T-cell subsets have been reported between HIV+ and HIV--patients with lymphoma." (PMID 24287598, 2013).
lymphoma (continued). "Lymphoma cells usually have the following phenotype: CD2+, CD3+, CD4−, CD5−, CD7+ and CD8−." (PMID 23145171, 2012). "There is no statistical difference in either CD4 counts or viral loads between the patients with and without nasopharyngeal lesions and between patients with and without lymphomas." (PMID 22991655, 2012). "Herein, we report that mice homozygously expressing a dominant negative TGFβRII (dnTGFβRII) under the control of the CD4 promoter spontaneously develop lymphoma-like T cell infiltration involving both spleen and liver." (PMID 23145171, 2012). "CD4+CD25+ FOXP3+CD127low Tregs are markedly increased in peripheral blood mononuclear cells (PBMCs) versus healthy controls regardless of lymphoma subtype, and correlated with disease stage and serum lactate dehydrogenase." (PMID 22151904, 2011). "It was also reported that a Hodgkin lymphoma cell line, which expressed galectin-1, had a negative effect on proliferation of CD4 T cells and that this effect diminished when the lymphoma cells knocked down for galectin-1 were added to the co-culture." (PMID 24212939, 2011). "Furthermore, a spontaneous T-cell leukaemia/lymphoma has been described in some African monkeys naturally infected with STLV-1, in which both CD4+ and CD8+ cells are involved." (PMID 19557183, 2009). "The researchers also studied a comparison group of cohort participants with comparable CD4+ cell counts but no PCNS lymphoma, and found that 13/16 of those participants did have CD4 responses to EBV." (PMID 17388662, 2007). "Three of these patients had low CD4+ cell counts prior to lymphoma diagnosis and three had normal CD4+ cell counts, but CD4 responses specifically against EBV were absent or very low in all six patients before they were diagnosed with PCNS lymphoma." (PMID 17388662, 2007). "We also found that one mouse developed both CD4- and CD8-rich lymphomas arising from the thymus and mesenteric lymph node, respectively, suggesting that 4OHT-induced Pten loss in different lymphoid origins may develop simultaneously (data not shown)." (PMID 18043744, 2007). "Here we observed—irrespectively of absolute CD4+ T cell counts—an almost complete lack of EBV-specific CD4+ T cells in HIV-positive patients who progressed to PCNS lymphoma." (PMID 17388662, 2007). "The therapeutic viruses use CD4 and CXCR4 for cell entry and could potentially be used against CXCR4 expressing malignancies such as T-lymphoblastic leukemia/lymphoma, NK leukemia and some myeloid leukemias." (PMID 17005036, 2006). "With respect to CD4 and CD8expression, the lymphomas were either double-negative (DN), double-positive (DP), orsingle-positive (SP)." (PMID 1322753, 1992). "In addition, the neoplastic cells in T-lymphoblastic leukemia/lymphoma do not exhibit variable CD4 and CD8 staining." (PMID 40227608, 2025). "However, the scenario of the local CD4+ T-cell immune response, particularly within germinal centers, the histological site where most lymphomas originate, has not yet been fully elucidated." (PMID 40963636, 2025). "None of the mice that were not subjected to CD4 depletion developed lymphomas." (PMID 39339897, 2024). "Histopathological analysis, with the aid of immunohistochemistry, revealed the identification of proteins among the lymphomas (n = 6), which acted as markers, the majority (n = 3) being positive for CD138 and for Ki-67 (n = 2), in addition to other markers, such as CD4, CD30, and CD43." (PMID 37958380, 2023). "In addition, another group recently showed that lymphoma immunoglobulin neoantigens are presented abundantly by MHC-II for CD4+ T-cell recognition, but not MHC-I." (PMID 36979775, 2023). "A total of five of the 25 cases, all in the C category, could not be assessed for CD4+ T-cell count categories, as patients had not had CD4+ counts performed in the eligible period for the study (three months before/three months after lymphoma diagnosis)." (PMID 37190220, 2023).